IL2 (interleukin 2)
Diseases named in the same sentence as IL2 in open-access papers (continued):
Sharing a sentence is not in itself a finding about the gene and the disease.
tumor (continued). "As IL-2R and/or GM-CSFR are widely expressed among immune cells and tumor cells, we supposed that IL2-GMCSF should be capable of enhancing cell–cell interactions by binding to both receptors and bridging them into close proximity." (PMID 26850448, 2016). "Interleukin (IL)-2 and granulocyte–macrophage colony-stimulating factor (GM-CSF) are among the most effective cytokines to induce tumor-specific systemic immune responses and can act synergistically." (PMID 26850448, 2016). "A water-soluble polysaccharide, called JRP1, isolated from Juglans mandshurica showed in vivo immunostimulatory effects by increasing the release of IFN-γ and IL-2 in an immunosuppressed model of mice bearing S-180 tumor." (PMID 27042188, 2016). "Granulocyte–macrophage colony-stimulating factor (GM-CSF) and IL-2 are among the most powerful cytokines to induce tumor-specific systemic immune responses in experimental models and clinical trials." (PMID 26850448, 2016). "NK cells from healthy donors upon activation with IL-2 and IL-15 kills indiscriminately both stem-like and differentiated tumor cells via stress ligand recognition." (PMID 27769244, 2016). "Vitiligo has been frequently reported in response to immunotherapy including IL-2 therapy, adoptive transfers of tumor-infiltrating lymphocytes, and other tumor vaccines." (PMID 27071457, 2016). "Only membrane Hsp70+ tumor patients will be recruited into the trial since membrane Hsp70 was identified as the tumor-specific target for Hsp70–peptide + IL-2 preactivated NK cells." (PMID 27199993, 2016). "Alternatively, combination therapy with IL-2 and IL-12 increased the capacity of activated NK cells to eliminate tumor cells." (PMID 27821119, 2016). "By contrast, IL-2 levels decreased upon in vitro tumor-stimulation of lymphoid cells from Salmonella-treated mice." (PMID 26973649, 2016). "Enforced expression of IL-2 by the T cells themselves results also in prolonged survival in vitro and maintains the tumor specificity and function." (PMID 27656185, 2016). "Administration of IL-2 significantly augmented the therapeutic efficacy of adoptively transferred tumor-draining lymph node (TDLN) B cells which express IL- 2R." (PMID 27528023, 2016). "Patient selection based on tumour morphology has helped achieve much-improved HD IL2 efficacy, and remains the cornerstone of our practice." (PMID 27777776, 2016). "The immunotherapy in this trial consisted of a tumor-specific mAb directed toward the tumor antigen GD2 in combination with administration of immune stimulating cytokines IL-2 and GM-CSF." (PMID 27471639, 2016). "After homogenization of a tumour, TILs are cultured for 1-2 weeks ex vivo with high dose of interleukin 2 (IL-2)." (PMID 27212807, 2016). "In these models, IL-2/anti-IL-2 complexes administered early after tumor inoculation significantly increased the survival rate of mice." (PMID 27391012, 2016). "In humans, the combination of ECT and IL2 administration was tested in melanoma patients and resulted in an increased number of antigens recognized by specific tumor-infiltrating T cells." (PMID 26993326, 2016). "There were 6 patients whose tumour contained sarcomatoid architecture and responded to HD IL2 (of whom 2 were complete)." (PMID 27777776, 2016). "Interleukin-2 (IL-2) is one of the most successful cytokines applied in tumor immunotherapy, which plays a key role in immune regulation and T cell proliferation." (PMID 27246873, 2016). "First, we compared the effects of ADT, vaccination, Treg depletion and IL-2 neutralization, either alone or combined with other treatments, on tumor growth." (PMID 26868634, 2016). "NK cells have been found to be especially sensitive to IL-2 and animal tumor model studies have found a dependence on activated NK cells in the induction of anti-tumor effects." (PMID 27153543, 2016). "More importantly, many studies proved that recombinant NDVs (rNDVs) expressing IL2 are promising anti-tumor agents." (PMID 27736965, 2016).
tumor (continued). "Rather than the IgG-IL2 immunocytokine, a combination of an anti-tumor antigen IgG antibody and an untargeted Fc-IL2 monomer was approached for synergistic anti-tumor immunotherapy." (PMID 27766096, 2016). "An additional promising approach demonstrated that exogenous IL-7 added to T cells co-cultured with tumor cells inhibited loss of CD28, a feature of replicative senescence, and allowed normal proliferative capacity and IL-2 production." (PMID 27809856, 2016). "And IL-2 has been successfully applied in treating a series of tumor cells in combination with other agent." (PMID 27015938, 2016). "Among the various ex vivo cytokine conditions, mice receiving CART cells with previous IL-2 exposure showed the least tumor control, consistent with the lowest number of circulating human T cells." (PMID 27409425, 2016). "Recent studies have indicated that adoptive transfer of less differentiated T cells correlates with superior tumor regression, that aligns with our finding that IL-2 exposed CART cells are less effective in vivo." (PMID 27409425, 2016). "In a subsequent experiment, sets of mice treated with PBMC+IL-2 were collected on days 7, 14 and 21 post-treatment to examine the human lymphocyte population and their interaction with the tumor in the intraperitoneal cavity." (PMID 26802025, 2016). "Together, these data support our conclusion that IL-2 modulates several pathways contributing to the killing of tumor cells by B effector cells." (PMID 27528023, 2016). "The studies reported here show high levels of granzyme in haNK cells, and demonstrate the effects of irradiation of haNK cells on multiple phenotypic markers, viability, IL-2 production, and lysis of a spectrum of human tumor cells." (PMID 27861156, 2016). "This was injected intratumorally into syngeneic tumor-bearing mice, and induced significant tumor growth suppression comparable to or higher than similar complexes expressing cytokines such as interleukin-2 (IL-2) and interleukin-12 (IL-12)." (PMID 26213962, 2015). "The baseline biomarkers for Nap exposure and/or low tumour induced immune suppression coincided with IL-2 production after Nap treatment as well as the expansion of Nap+ T cells." (PMID 25669986, 2015). "The addition of IL-2+anti-CD16mAb also significantly inhibited the NK cell cytotoxicity against both tumor cell lines when compared to IL-2 activated NK cells (p < 0.05)." (PMID 26247631, 2015). "Although using IL-2 to stimulate the proliferation of anti-tumor T cells in culture remains the standard clinical approach, we were encouraged by our results with IL-7/15 to add or substitute IL-21 to our expansion regimen." (PMID 25903148, 2015). "The proinflammatory molecule IL-2, which enhances tumor cytotoxicity by inducing proliferation and activation of T and NK cells, is the cytokine that has been most extensively studied in adult as well as childhood AML." (PMID 26124967, 2015). "The use of IL-2 has been shown to lead to a complete tumor response and durable long-term survival in a small percentage of patients." (PMID 26557408, 2015). "CD8+ T cell responses against six different tumor-associated antigens (TAA) were characterized by IFN-γ ELISPOT and IFN-γ/IL-2 DualSpot assays." (PMID 26116238, 2015). "This central memory phenotype has been suggested in multiple studies to be more effective at inducing tumor regression than terminally differentiated effector cells, which are more likely to be selectively expanded when T cells are grown in IL-2." (PMID 25903148, 2015). "It is possible therefore that IL-2 is limited in the tumor microenvironment and that the perturbation in Tconv to Treg ratios reflects competition for limited IL-2 at this site." (PMID 26433463, 2015). "Significant inhibition of NK cell cytotoxicity by monocytes can be observed against untreated or IL-2 treated NK cells against both tumor types (p < 0.05)." (PMID 26247631, 2015).
tumor (continued). "Pro-inflammatory cytokines, including IFN-γ, TNF-α, and IL-2 are critical in tumor initiation, promotion, and progression." (PMID 26098776, 2015). "Secreted IL-2 is known to be a key factor for T-cell activation and for the anti-tumor effect of BsAb therapy." (PMID 26678395, 2015). "Such CD86-expressing irradiated autologous tumor cell vaccines have been evaluated in combination with subcutaneous IL-2 administration in a phase II study involving 66 stage IV renal cell carcinoma patients." (PMID 26343191, 2015). "Whereas, decreases in OSCSCs and MP2 resistance were observed when fixed NK cells treated with anti-IFN-γ and IL-2 + anti-CD16mAb + sAJ2 were used to differentiate both tumor cell lines." (PMID 26697005, 2015). "Interleukin-2-loaded polymeric nanoparticle inhibited the tumor growth and can lengthen survival in mice B16F1-bearing melanoma." (PMID 26078967, 2015). "In this study, we investigated the effect of SCL on the production of cytokines, including TNF-α, IFN-γ, IL-2 and IL-6, in H22 tumor-bearing mice." (PMID 26426041, 2015). "Recently, the clinical interest of using IL-15 was further strengthened because IL-2 administration also expanded regulatory T cells, which suppress the anti-tumor response of NK cells and effector T cells." (PMID 26257729, 2015). "Following ex vivo activation with anti-CD3 and culture with interleukin-2 (IL-2), these preeffector cells acquire tumor-specific effector function against established tumor in vivo." (PMID 26090481, 2015). "In it, peripheral blood mononuclear cell (PBMC)-derived T cells exposed to tumor cells were injected intralesionally, and into metastatic lymph nodes, pleural and peritoneal spaces along with IL-2, yielding complete or partial responses in 36.4% (4/11)." (PMID 29546098, 2015). "Taken together, our results indicate that local tumor treatment with carefully selected immunomodulatory cytokine (such as IFN-α2, IFN-γ and IL-2) can result in favorable alteration of tumor microenvironment and thus affect T-cell activity within the tumor." (PMID 26107883, 2015). "Tumor-derived IDO promotes production of the immunosuppressive tryptophan catabolite l-kynurenine that interferes with IL-2 induced expression of NKp46 and NKG2D receptors that are required for target cell recognition and killing." (PMID 25972872, 2015). "The basic IL-2 property is to activate effector cells to selective lysis of freshly isolated tumour cells." (PMID 25976216, 2015). "In the specific case of EAT 90% of tumor-bearing mice were cured with a combination therapy consisting of the administration of indomethacin and IL-2." (PMID 26347589, 2015). "Expression of inflammatory cytokines such as IFN-γ, TNF-α, and IL-2 as well as IL-10 expression in draining lymph nodes (LNs) was significantly reduced in kCYC mice after tumor inoculation." (PMID 26098776, 2015). "In this therapy, a section of a patient’s tumor is excised and grown in culture in the presence of IL-2 to promote the selection of lymphocytes, which overgrow and destroy the tumor cells within 2–3 weeks." (PMID 27066495, 2015). "Preclinical data have shown that stimulation of NK cells with Hsp70 peptide TKD plus IL-2 results in an increased migratory capacity of NK cells and an enhanced killing of Hsp70 membrane-positive tumor cells in vitro, and in relevant tumor mouse models." (PMID 25926832, 2015). "Regarding these results, we concluded that Hsp70-positive tumor cells are killed by Hsp70 plus IL-2 activated, CD94-positive NK cells via granzyme B-mediated apoptosis." (PMID 25926832, 2015). "We employed a strategy consisting of N-bis infusion to sensitize tumor cells, followed by the adoptive transfer of 2M3B1PP-stimulated Vγ9Vδ2 T cells and low-dose IL-2." (PMID 25686210, 2015).
tumor (continued). "High-dose IL-2 presumably mediates anti-tumor activity through expansion of the CD8+ T cell and NK cell compartments, but it is also known to expand regulatory CD4+ FoxP3+ T cells (Tregs), which can mediate immune suppression and promote peripheral tolerance." (PMID 25992289, 2015). "CTLA-4 blockade increased immune cell infiltration (including CD8+ T cells and NK cells) in the tumor and IL-2 reduced the proportion of highly differentiated/exhausted tumor-infiltrating NK cells." (PMID 25992289, 2015). "The immunogenic cell death induced by radiation would increase tumor-targeting of NHS-IL2, leading to an enhanced activation of tumor-specific cytotoxic T-lymphocytes (CTLs) and other immune effector cells via the low-toxicity formulation of IL-2." (PMID 25622640, 2015). "Along these lines, heat shock protein vaccination and directed IL-2 therapy amplify tumor immunity rapidly following bone marrow transplantation in mice." (PMID 25590298, 2015). "The results obtained allow us to infer that the EAT inoculation stimulated PGE2 production throughout its development and that the neoplasm growth has a positive influence on the production of IL-2 and IL-6 in the 13th day of tumor development." (PMID 26347589, 2015). "IL2 that was produced by the CD4+ T cells alone (the value was 48.7 ± 7.3 pg/ml) significantly increased when CD4+ T cells were incubated with tumor cells and the diabody ( 333.0 ± 22.5 pg/ml)." (PMID 26444983, 2015). "There are many cytokines secreted by aHSCs that are associated with tumor invasion and metastasis, including HGF, EGF, IL-1, IL-2, IL-6, MMP-2, MMP-9, TGF-β, TNF-α, VEGF and members of the Wnt signaling family." (PMID 26517671, 2015). "The results obtained in the measurement of cytokines showed that the EAT promoted release of IL-2 and IL-6 in the 13th day of tumor development." (PMID 26347589, 2015). "Second, the ICK was used to target the tumor expressing CEA via the antibody portion M5A, and home in the targeting of NK cells, which express IL-2 receptors, to the tumor site via the cytokine IL-2." (PMID 26556731, 2015). "Dieli and coworkers conducted a phase I clinical trial to determine the anti-tumor effect of the single or combined administration of Zol and IL-2 in patients with metastatic castration-resistant prostate cancer (CRPC)." (PMID 25686210, 2015). "We demonstrated that interleukin-2 (IL-2) transgenic EFT cells can induce immune responses against wild-type tumor cells in vitro and in a xenotransplantation model." (PMID 26579494, 2015). "These IL-2 and IL-21 exposed splenocytes, perhaps unsurprisingly, were the least efficacious at curing or slowing tumor growth." (PMID 25903148, 2015). "Other mAb therapies, such as rituximab and trastuzumab, are also being combined with IL2 in clinical trials to evaluate the anti-tumor efficacy." (PMID 26284063, 2015). "A comparison of results for a given patient during anti-tumour therapy with regard to salivary IL-2 showed significant differences between examination 2 and examination." (PMID 25976216, 2015). "Such a normalizing IL-2 potential for effector and regulatory T cell distribution has already been described in the tumor and the infection microenvironment." (PMID 25145773, 2015). "Adoptive cell therapy (ACT), based on autologous T cells expanded with tumor antigens and IL-2 ex vivo, is envisioned to induce tumor regression as a “live drug”." (PMID 26350600, 2015). "In this orthotopic renal and metastatic lung tumors models, YM155 and IL-2 additively decreased tumor weight, lung metastasis, and luciferin-stained tumor images." (PMID 26023798, 2015). "In this trial, which is recruiting participants, patients will receive immune suppressive therapy with pentostatin, followed by bortezomib to sensitize tumor cells to NK cytotoxicity, escalating doses of autologous NK cells and IL-2." (PMID 26029215, 2015).
tumor (continued). "IL-2 has been demonstrated to serve an important role in specific immunological responses to tumor cell growth." (PMID 25371265, 2015). "The autophagy inhibitor chloroquine synergistically enhanced IL-2 immunotherapeutic efficacy and inhibited tumor growth in a dose-dependent fashion." (PMID 25590298, 2015). "Since cytokines play a key role in controlling immune responses and inflammatory reactions, we employed the ELISA assay to investigate the effects of SCL on the production of serum cytokines, including TNF-α, IFN-γ, IL-2 and IL-6, in H22 tumor-bearing mice." (PMID 26426041, 2015). "The objective of the study was to assess the effect of disturbed immunity on the gum condition and saliva interleukin-2 (IL-2) concentration in children with acute lymphoblastic leukaemia (ALL) during anti-tumour treatment." (PMID 25976216, 2015). "A comparison of results for a given patient during anti-tumour therapy with regard to salivary IL-2 showed significant differences between study 2 and study 3 (Wilcoxon signed-rank test; Z = 2.173; p = 0.0297)." (PMID 25976216, 2015). "Among the tumor-infiltrating CD8+ T cells, TIM-3+ cells produced more IFN-γ, TNF-α and IL-2 compared to that by TIM-3- cells when tested by intracellular staining on day 28- post tumor inoculation." (PMID 26493689, 2015). "When tumor cells stimulated by Ara-C and diabody were added, IL2 released by T cells was much more higher (869.1 ± 134.6 pg/ml)." (PMID 26444983, 2015). "Despite the polyclonal nature of the cell culture with anti-CD3 and IL-2, the resultant T cells mediate in vivo antitumor effect only against the tumor with which they were stimulated in vivo." (PMID 26090481, 2015). "Genetic introduction of interleukin 2 (IL2) into EG.7 (ovalbumin-expressing) tumor cells resulted in the presence of IL2 in (or on) TEX from those cells." (PMID 26694473, 2015). "High levels of tumor suppression were observed after peritumoral injection of the polymeric nanoparticle with interleukin-2, which prolonged survival in mice; thus, it is a promising gene-based therapeutic strategy for MEL." (PMID 26078967, 2015). "Originally defined by secretion of IL-2 or IL-10, which in turn activates Th1 or Th2 cells, now the concepts of M1/M2 subtypes basically represent tumor suppressive or tumor supportive macrophages, albeit a little bit oversimplified." (PMID 24675569, 2014). "In the present study, in which tumor-bearing mice were treated with Ad-hLF, the level of serum IL-2 was increased, which indicates that hLF activates NK cells." (PMID 24520300, 2014). "Other investigators found that a modest dose of Dox had the potential to boost immune response and potentiate the IL-2 effect against tumor cells." (PMID 24565056, 2014). "This study further confirmed the requirement for the combination of IL-2 or IL-15 with anti-CD40 mAb for tumor regression versus the partial effects seen with anti-CD40 mAb treatment alone in large tumor burdens." (PMID 24955376, 2014). "So the effects of intralesional treatment with a plasmid containing bacterial superantigen gene (staphylococcal enterotoxin A, SEA) plus immunostimulatory canine IL-2 gene before surgical resection or exploration and biopsy of the tumor bed were reported." (PMID 25506617, 2014). "In a rat glioma model, no therapeutic effect was observed in animals treated with intradermally injected paraformaldehyde-fixed tumor vaccine alone, but intratumoral injection of IL-2-activated rat NK cells strongly enhanced antitumor effect of the vaccine." (PMID 25009822, 2014). "The cells were co-cultured with different tumor lines and analyzed for IFNγ and IL-2 secretion as well as activation marker upregulation." (PMID 25431955, 2014). "Similar findings were observed by Cha and coworkers, who showed that 4T1 specific T cells grown in IL-2 media are able to inhibit 4T1 tumor growth." (PMID 25334026, 2014).